CD9 (CD9 molecule)
Diseases named in the same sentence as CD9 in open-access papers (continued):
Sharing a sentence is not in itself a finding about the gene and the disease.
acute lymphoblastic leukemia (9 papers, 2014 to 2024). Leukemia with an acute onset, characterized by the presence of lymphoblasts in the bone marrow and the peripheral blood. "In acute lymphoblastic leukemia, CD9 seems to be associated with cancer stem cell properties, is involved in leukemic progression, and is related to unfavorable outcomes." (PMID 33918035, 2021). "Although CD9 seems to be associated with unfavorable outcome and disease progression in acute lymphoblastic leukemia (ALL), this marker has not yet been studied in acute myeloid leukemia (AML)." (PMID 30740913, 2019). "For example, in acute lymphoblastic leukemia, CD9 expression indicates a poor outcome." (PMID 30356731, 2018). "Also, in other tumors, CD9 has been reported as a cancer stem cell biomarker, for example in mesothelioma and in lymphoblastic leukemia cells." (PMID 26573230, 2016). "Finally, CD9 expression can predict a TEL/AML1 rearrangement in acute lymphoblastic leukemia." (PMID 33918035, 2021).
asthma (9 papers, 2018 to 2025). "Functional impairments or defects in CD9+ IL-10-secreting regulatory B cells are associated with enhanced asthma-like inflammation and airway hyperresponsiveness." (PMID 30622536, 2018). "Clinical samples have also shown a significant reduction of CD39+CD9+ IMs in patients with severe asthma, indicating their potential as therapeutic targets." (PMID 40636260, 2025). "We identified several significant mediation genes including INAGL1, SERPINE1, TLR5, SLC9A3 and CD9 for asthma severity and INAGL1, TLR5, CD9 for FEV1, suggesting potential regulation effect of DNAm on gene expression in asthma." (PMID 38245772, 2024). "In the house-dust-mite-induced murine asthma model, a CD9+ Breg cell subset was identified as the major inhibitor of the asthmatic responses." (PMID 37759658, 2023). "In mice, the adoptive transfer of CD9+ B cells reverses asthma, and the adoptive transfer of CD1dhi Bregs suppresses airway inflammation by inducing natural forkhead box protein 3-positive CD4+ regulatory T cell recruitment into the lungs." (PMID 30622536, 2018). "The unique link between CD9 and asthma is related to the observation that certain tetraspanins interact with tetrameric high-affinity IgE receptors (FcεRI) on effector cells." (PMID 30622536, 2018). "The adoptive transfer of these CD9+ B cells alone is thus sufficient to abrogate asthma in an IL-10-dependent manner." (PMID 30622536, 2018). "We have previously demonstrated that murine IL-10+ Bregs are enriched in a CD9+ B cell subset and that adoptive transfer of CD9+ B cells alone is sufficient to abrogate asthma in an IL-10-dependent manner." (PMID 30622536, 2018). "Increasing the number of regulatory B cells, including CD9+ Breg, is under consideration as an interesting target for the development of new therapies to regulate inflammation in asthma and other allergic diseases to induce allergen tolerance." (PMID 30356731, 2018). "Induction of allergic asthma in mice alters the homeostasis of IL-10+ Bregs, and adoptive transfer of CD9+ B cells alone is sufficient to abrogate asthma in an IL-10-dependent manner." (PMID 30622536, 2018). "Furthermore, a CD39+CD9+ lung interstitial macrophage identified in neutrophil-dominant asthma mitigates IL-23/Th17-mediated neutrophilic inflammation through CD9-dependent neutrophil adhesion and CD39-dependent ATP hydrolysis." (PMID 41188606, 2025). "CD9 was also upregulated, and it has been used as a surface marker of eosinophils in asthma." (PMID 31832069, 2019). "In mouse models, all asthma-related features can be abrogated by CD9+ B cell adoptive transfer." (PMID 30622536, 2018). "Finally, in the context of allergic asthma, there are fewer CD9+ B cells in the spleen and lungs of asthmatic mice, and the adoptive transfer of CD9+ B cells alone is sufficient to abrogate asthma in an IL-10-dependent manner." (PMID 30356731, 2018). "Saliva EVs from this cohort of children with asthma are 64.95 nm in diameter on average, with a median of 55.09 nm, as reported by TEM, and express mostly CD9 and CD63." (PMID 34368811, 2021). "All together, we report that patients with severe asthma and asthmatic mice both harbor a defect in number of CD19+CD9+ B cells." (PMID 30622536, 2018). "Moreover, in neutrophilic asthma, a phenotype of asthma that is unresponsive to glucocorticoids, a regulatory CD39+CD9+ IMs subpopulation has been identified." (PMID 40636260, 2025). "Defects in CD9+ B cells in blood from patients with severe asthma reveal new insights into the lack of regulation of inflammation in these patients." (PMID 30622536, 2018). "Patients with severe asthma and asthmatic mice both harbored less CD19+CD9+ B cells, although these cells displayed no defect in their capacity to induce T cell apoptosis." (PMID 30622536, 2018).
bladder cancer (9 papers, 2008 to 2025). "After 5637 bladder cancer cells were co-incubated with HEK293-derived CD9-RFP CS/NACS-carrying EVs, vesicular uptake was first recorded every hour for 24 hours as red fluorescence emission." (PMID 36579638, 2023). "Western blot analysis of EVs isolated from three bladder cancer cell lines showed the presence of the exosome markers Alix, CD9, and TSG101." (PMID 29207636, 2017). "This is in line with evidence from studies with ovarian and bladder carcinoma cell lines that low-level CD9 expression triggers tumor cell motility and invasiveness." (PMID 27572323, 2016). "Some gangliosides, such as GM3 and GM2, inhibited cell motility facilitated by the tetraspanins CD9 and CD82 in some tumor cell lines (for example, colorectal, haptotactic, and bladder cancer cells)." (PMID 18171481, 2008). "We selected generic exosome markers CD9, CD63, and TSG101, as well as the EDIL-3 and MUC4 for Western blotting analysis of urinary exosome proteins prepared by UC and NanoPoms methods, with the human bladder carcinoma cell line HTB9 as the control." (PMID 35787656, 2022).
periodontitis (9 papers, 2020 to 2025). An acute or chronic inflammatory process that affects the tissues that surround and support the teeth. "Regarding surface markers, significantly decreased CD9 and CD81 were detected in periodontitis and correlated with disease stage, although another study reported an increase in the CD9+ subpopulation, suggesting that the diagnostic value of CD9 requires further validation." (PMID 41153802, 2025). "However, only CD81 remained independently associated with periodontitis after adjusting for confounding variables, whereas the association of CD9 was attenuated by demographic covariables, limiting its diagnostic relevance." (PMID 41322905, 2025). "Patients with stages II, III, and IV exhibited lower CD9 concentrations than those with stage I periodontitis, while CD81 levels were significantly reduced in stages III and IV." (PMID 41322905, 2025). "Beyond the presence of immune-related proteins, salivary exosomes in periodontitis exhibit significantly reduced levels of the tetraspanins CD9 and CD81." (PMID 41322905, 2025). "In patients with periodontitis, salivary samples demonstrated decreased levels of exosomal CD9 and CD81, when compared to healthy controls." (PMID 38610017, 2024). "For instance, contradictory findings were observed regarding the levels of salivary exosomal CD9 in periodontitis." (PMID 38610017, 2024). "The first study highlights the association between reduced levels of CD9 and CD81 exosome-related tetraspanins in saliva and periodontitis, particularly in more severe cases." (PMID 38192959, 2023). "According to another study, patients with periodontitis had considerably fewer CD9+ and CD81+ saliva exosomes than healthy controls." (PMID 37114060, 2023). "Subsequent flow cytometry assay confirmed that loss of OTUD1 facilitated CD9 and CD47 surface expression in neutrophils during periodontitis and peritonitis." (PMID 37639212, 2023). "A recent report demonstrated salivary CD9+ and CD 81+ sEVs were decreased in periodontitis patients, while another report showed that salivary CD63+ sEVs are comparable in periodontitis and non-periodontitis patients." (PMID 33670900, 2021). "Using our in-house CD9 enzyme-linked immunosorbent assay (ELISA), we found that CD9 in saliva and CD9+ sEVs were comparable between the healthy, gingivitis and periodontitis groups." (PMID 33670900, 2021). "It has been shown that CD9/CD81-positive salivary sEVs were decreased in periodontitis patients compared to healthy controls." (PMID 33670900, 2021). "Additionally, this review found that salivary exosomal tetraspanins CD81 and CD9 were reduced in advanced periodontitis (stages II-IV, grade C), although only CD81 remained independently associated." (PMID 41322905, 2025). "Interestingly, although EV size and morphology remained consistent across participants, the CD9 + subpopulation was more prevalent in those with periodontitis." (PMID 38610017, 2024). "Recent research findings suggest that CD9 positive salivary sEV are decreased in periodontitis patients when compared to periodontally healthy controls; with a limitation of this study being the lack of a gingivitis group and the sEV being isolated using the EQ method." (PMID 32722322, 2020). "A recent study utilizing salivary sEV, isolated using an EQ kit, as potential biomarkers for periodontal disease status, suggested that CD9 and CD81 were decreased in periodontitis patient-derived sEV when compared with healthy controls." (PMID 32722322, 2020). "Salivary exosomal cargo in periodontitis includes complement components C6, C8A, C8B, and chemokine CCL28, together with decreased CD9/CD81 and elevated PD-L1 mRNA, which may indicate altered immune regulation and correlate with disease severity." (PMID 41322905, 2025).
periodontitis (continued). "It is suggested that the decreased levels of CD9 and CD81 may disrupt molecular organization within the periodontal microenvironment, potentially contributing to tissue destruction and bone resorption in periodontitis." (PMID 41322905, 2025).
acute myeloid leukemia (8 papers, 2019 to 2025). Acute myeloid leukemia (AML) is a group of neoplasms arising from precursor cells committed to the myeloid cell-line differentiation. "Conversely, in acute myeloid leukemia, CD9 is associated with a favorable outcome and could be a very relevant marker for minimal residual disease monitoring." (PMID 33918035, 2021). "Research on CD9 expression has been extensive in B lymphoblastic leukemia, with fewer studies focusing on acute myeloid leukemia (AML)." (PMID 40972677, 2025). "CD9 is a tetraspanin molecule that is expressed on a wide variety of hematopoietic cells as precursor B cell, megakaryocytes, and certain acute myeloid leukemias." (PMID 33236622, 2020). "CD9 mediates chemoresistance in acute myeloid leukemia and small cell lung cancer." (PMID 36941633, 2023). "CD9 enhances the stemness and chemoresistance of acute myeloid leukemia cells." (PMID 36941633, 2023).
mesothelioma (8 papers, 2013 to 2025). A usually malignant and aggressive neoplasm of the mesothelium which is often associated with exposure to asbestos. "In this study, we identified CD9 as an independent predictor of survival, and loss of expression showed biological aggressive behavior in mesothelioma cells." (PMID 23128478, 2013). "Similar results were also seen in the mesothelioma cell line NCI-H2452 transduced with CD26 or CD9 siRNA." (PMID 24466195, 2014). "In order to understand the nature of the association between CD26 and CD9, we performed microarray analysis of CD26-depleted and CD26 over-expressed mesothelioma cells." (PMID 24466195, 2014). "This study is the first to analyze CD9 expression in human mesothelioma tissue and to correlate its expression with survival with other clinicopathological parameters." (PMID 23128478, 2013). "Multivariate analysis identified CD9 expression as an independent prognostic factor with a hazard ratio (HR) of 1.99 in the analysis of all mesotheliomas (P=0.0261) and an HR of 2.60 in the analysis of EMs (P=0.0376)." (PMID 23128478, 2013). "Histologically, CD9 immunoreactivity was observed in 62 of 71 epithelioid mesotheliomas, 13 of 20 biphasic mesotheliomas and only 1 of 21 SMs." (PMID 23128478, 2013). "CD9 expression was observed in 62 of 71 epithelioid, 13 of 20 biphasic and only 1 of 21 sarcomatoid mesotheliomas." (PMID 23128478, 2013). "This suggests the importance of CD9 expression as an indicator for patients receiving chemotherapy in mesothelioma patients." (PMID 23128478, 2013). "Immunohistochemical analysis of CD9 expression in the patient mesothelioma samples indicated that CD9 expression was a favorable prognostic factor." (PMID 23128478, 2013). "At the opposite end and in accordance with its controversial role in cancer, CD9 expression in mesothelioma tissue correlates with survival and may be a favorable prognostic marker in patients with mesothelioma." (PMID 30356731, 2018). "In conclusion, our present study demonstrates that the interaction between CD26 and CD9 mediates mesothelioma behavior, while suggesting that CD26 and CD9 would be promising biomarkers as well as molecular targets for the future treatment of malignant mesothelioma." (PMID 24466195, 2014). "Furthermore, overexpression of CD9 on the CD26-positive mesothelioma cell line NCI-H226 decreased CD26 expression and suppressed invasion." (PMID 24466195, 2014). "Therefore, we investigated the effects of CD9 on the cell migration of mesothelioma cell lines using shRNA-mediated CD9 knockdown." (PMID 23128478, 2013). "In conclusion, CD9 expression is a favorable prognostic marker in patients with mesothelioma." (PMID 23128478, 2013). "We found increased cell migration in CD9-knockdown mesothelioma cell lines." (PMID 23128478, 2013). "Hence, we performed multivariate analysis of patients with epithelioid mesothelioma alone and we again found that CD9 expression was a predictor of survival of mesothelioma patients with an HR of 2.60 (P=0.0376), suggesting the independent prognostic value of CD9 expression in mesothelioma." (PMID 23128478, 2013). "Meanwhile, these molecules exhibited opposite effects on invasion and migration of mesothelioma cells, with CD26 having an enhancing effect and CD9 showing a suppressing effect." (PMID 24466195, 2014). "We found increased cell migration in the mesothelioma cell lines MSTO-211H and TUM1 following in vitro shRNA-mediated knockdown of CD9 expression." (PMID 23128478, 2013). "Thus, CD9 may be a potential candidate as a molecular target in the treatment of mesothelioma." (PMID 23128478, 2013). "Moreover, we previously identified CD9, along with side population, CD24 and CD26 cells, as a cancer stem cell marker of mesothelioma, thus demonstrating its potential for cancer stem cell-targeted therapy in the future." (PMID 23128478, 2013).
mesothelioma (continued). "Moreover, we previously identified CD9 along with side population CD24 and CD26 cells to be markers of cancer stem cells in mesothelioma." (PMID 23128478, 2013). "CD9 depletion led to increased FAK and Cas-L tyrosine phosphorylation in mesothelioma cells, indicating that CD26 and CD9 may regulate the overall protein level and tyrosine-phosphorylation of β1 integrin-related signaling molecules as well as the expression of α5β1 integrin." (PMID 24466195, 2014).
viral infection (8 papers, 2017 to 2025). "For example, CD9(+) sEVs derived from dendritic cells can activate T cells and augment the immune response to viral infections." (PMID 37371093, 2023). "It is known that CD81 participates, in concert with other tetraspanins, like CD63 and CD9, in many biological processes such as cell adhesion, migration, cell–cell fusion as well as in multiple steps of viral infection, especially in the case of HIV-1." (PMID 36988579, 2023). "When considering the effect of CD63 (and to some extent CD9) depletion on viral infection, our results might appear surprising at first sight." (PMID 37198427, 2023). "Therefore, this low-CD9 expression level represents the CD9 optimum which enables efficient virus infection." (PMID 32385608, 2020). "CD81, CD63, and CD9 signals on CSF EVPs were significantly decreased in the viral disease group (p = 0.005, p = 0.0151, and p = 0.0050, respectively) compared to the non-viral disease group, although this trend is likely heavily influenced by the HAM patient CSF EVPs (open blue circles)." (PMID 37622115, 2023). "Taken together, our data suggest that exosomal proteins are depleted under infection conditions, which is reflected by the enrichment of ALIX and CD9 in the exosomal fraction under ZIKV infection conditions, indicating an increase in the number and size of the EVs in the context of viral infection." (PMID 40572291, 2025). "However, studying the biogenic proteins of exosomes in viral infections is crucial because tetraspanins, such as CD81, CD63, and CD9, are involved in viral release and regulate the increase in exosome production." (PMID 40572291, 2025). "Additional powerful biomarkers were identified for Pacific (Trim21, IFI) and Atlantic (CD9, RAD1, SACS, XAF1) salmon whereby assays did not work across species; if re-designed, these biomarkers may also contribute to the universal separation of viral disease states across species." (PMID 28702195, 2017).
atherosclerosis (7 papers, 2017 to 2025). A disease characterized by the build-up of fatty material and calcium deposition in the arterial wall resulting in partial or complete occlusion of the arterial lumen. "Blood transcriptomes revealed pyridoxal 5’phosphate salvage, pyrimidine ribonucleotides salvage pathways, atherosclerosis, and cell movement signaling with membrane CD9 and extracellular lysozyme as effectors." (PMID 28053879, 2017). "Results demonstrated that CD9 was mainly co‐localized with α‐SMA, indicating that ox‐LDL‐M‐EVs were mainly internalized by VSMCs in the plate, but not macrophages, thereby regulating the occurrence and development of atherosclerosis in regulation of the VSMC function." (PMID 34910364, 2022).
metastatic tumors (7 papers, 2020 to 2025). "CD9 shows that the tumor grade was inversely proportional to its expression, which is characterized by high expression in low-grade tumors and low expression in high-grade tumors or metastatic tumors." (PMID 36110943, 2022). "Importantly, some of these genes (THBS1, MAPKAPK2, CD9, TXNIP) were strongly associated with IL-6 signaling, indicating that IL-6 or its associated genes are coupled with metastatic tumors, in alignment with our previous findings." (PMID 34140316, 2021). "Conversely, CD9, TSPAN6, and TSPAN8 were downregulated in the tumor compartment of metastatic tumor." (PMID 38255741, 2024). "On the other hand, CD9, TSPAN6, and TSPAN8 were downregulated in the tumor compartment of metastatic tumor." (PMID 38255741, 2024). "The presence of EV was confirmed on western blot by the presence of EV-enriched proteins CD9, CD63, CD81 and TSG101 in SEC fractions 7 to 10 isolated from a healthy control and a patient with metastatic disease." (PMID 37046768, 2023).